HERC5 (HECT and RLD domain containing E3 ubiquitin protein ligase 5)
Description:
Major E3 ligase for ISG15 conjugation. Acts as a positive regulator of innate antiviral response in cells induced by interferon. Functions as part of the ISGylation machinery that recognizes target proteins in a broad and relatively non-specific manner. Catalyzes ISGylation of IRF3 which results in sustained activation, it attenuates IRF3-PIN1 interaction, which antagonizes IRF3 ubiquitination and degradation, and boosts the antiviral response. Mediates ISGylation of the phosphatase PTEN leading to its degradation, thus alleviating its suppression of the PI3K-AKT signaling pathway and promoting the production of cytokines that facilitate bacterial clearance. Interferes with the function of key viral structural proteins such as ebolavirus structural protein VP40 or HIV-1 protein GAG. Catalyzes ISGylation of influenza A viral NS1 which attenuates virulence; ISGylated NS1 fails to form homodimers and thus to interact with its RNA targets. Catalyzes ISGylation of papillomavirus type 16 L1 protein which results in dominant-negative effect on virus infectivity. Physically associated with polyribosomes, broadly modifies newly synthesized proteins in a cotranslational manner. In an interferon-stimulated cell, newly translated viral proteins are primary targets of ISG15. Promotes parkin/PRKN ubiquitin E3 ligase activity by suppressing the intramolecular interaction that maintains its autoinhibited conformation. (Microbial infection) Functions as an E3 ligase for ISGylation of hepatitis B virus protein X leading to enhanced viral replication due to increased interferon resistance.
Synonyms: CEB1; CEBP1
Tractability: PROTAC: UniProt records ubiquitination sites on it; ubiquitination databases record sites on it.
Gene: Protein-coding gene on chromosome 4 (88,457,086 to 88,506,188, forward strand). Ensembl gene ENSG00000138646.
Subcellular location: Cytoplasm, perinuclear region; Cytoplasm
Pathways (Reactome):
Immune System: Antigen processing: Ubiquitination & Proteasome degradation; DDX58/IFIH1-mediated induction of interferon-alpha/beta; ISG15 antiviral mechanism; Modulation of host responses by IFN-stimulated genes; Negative regulators of DDX58/IFIH1 signaling; PKR-mediated signaling
Disease: RSV-host interactions
Gene Ontology:
Molecular function: ISG15 ligase activity; ISG15 transferase activity; protein binding; RNA binding; ubiquitin protein ligase activity; ubiquitin-protein transferase activity
Biological process: antiviral innate immune response; innate immune response; ISG15-protein conjugation; positive regulation of cGAS/STING signaling pathway; protein ubiquitination; regulation of defense response to virus; PKR/eIFalpha signaling; regulation of cyclin-dependent protein serine/threonine kinase activity; ubiquitin-dependent protein catabolic process
Cellular component: cytoplasm; cytosol; perinuclear region of cytoplasm
Genetic constraint (gnomAD): Loss-of-function variants: 44 observed, 60.89 expected, observed/expected ratio (o/e) 0.72, 90% interval 0.57 to 0.93. The upper end of that interval is the gene's LOEUF score, 0.93, which puts it in group 3 of 6, group 1 being the genes least tolerant of losing a copy. Missense variants: 803 observed, 754.68 expected, observed/expected ratio (o/e) 1.06, 90% interval 1 to 1.13. Synonymous variants: 327 observed, 284.67 expected, observed/expected ratio (o/e) 1.15, 90% interval 1.05 to 1.26.
Homologues: Orthologues: chimpanzee HERC5 (98% identical), macaque HERC5 (95% identical), dog HERC5 (77% identical), pig HERC5 (70% identical), guinea pig Herc5 (62% identical). Paralogues in human: HERC6 (49% identical), HERC4 (35% identical), HERC3 (34% identical), HERC2 (26% identical), UBE3A (19% identical), HECW1 (17% identical), HECW2 (17% identical), HECTD4 (17% identical), NEDD4L (16% identical), HECTD1 (16% identical), HUWE1 (16% identical), HECTD2 (16% identical), and 12 more.
Diseases named in the same sentence as HERC5 in open-access papers:
HERC5 is named in the same sentence as 55 diseases in open-access papers, as found by Europe PMC text mining. Sharing a sentence is not in itself a finding about the gene and the disease. The quoted sentences say what the papers report.
viral infection (16 papers, 2014 to 2025). "Five hub genes shared by RA, COVID-19, and SAB were IFI44, OAS1, IFI44L, ISG15, and HERC5, and they were found to be closely associated with the immune system response to viral infection and bacterial infection using Metascape analysis." (PMID 36189314, 2022). "HERC5 catalyzes the ISGylation of target proteins, a process akin to ubiquitination that modifies proteins to help in the immune response against viral infections." (PMID 40742121, 2025). "Currently, HERC5 satisfies 3 of the 4 hallmarks of restriction factors: HERC5 exhibits strong ‘signatures’ of positive selection, is up-regulated by IFNβ and virus infection, and has antiviral activity as its major biological function." (PMID 24693865, 2014). "E3 ligase HECT and RCC1-containing protein 5 (HERC5) regulate interferon-stimulated gene 15 (ISG15) signaling in response to SARS-CoV-2 and other viral infections." (PMID 36510222, 2022). "Recent biochemical studies have demonstrated how the E3 ligase HECT and RCC1-containing protein 5 (HERC5) regulates ISG15 signaling in response to hepatitis C (HCV), influenza-A (IAV), human immunodeficiency virus (HIV), SARS-CoV-2 and other viral infections." (PMID 34207696, 2021). "Herc5, induced by the type I IFNs or viruses, functions as an ISG15 E3 ligase to promote overall ISGylation in response to viral infection and plays a role in host antiviral response." (PMID 34680952, 2021). "It is well known that type-I IFN induces potent cellular defense against viral infection mediated by up-regulation of ISGs like IFI44, IFI44L, and HERC5." (PMID 31749827, 2019). "HERC5 expression is up-regulated in response to IFN, in vitro and in vivo virus infection, lipopolysaccharide, tumor necrosis factor α, and interleukin-1β." (PMID 24693865, 2014). "Furthermore, viral infection induces expression of ISGylation enzymes, including UBE1L, UBCH8, ISG15, and HERC5, suggesting that ISGylation is involved in host defenses against viruses." (PMID 37651190, 2023). "Viral infection, represented by SARS-COV-2 infection, and type I IFNs induced expression of ISG15 and the predominant E3 ISGylation ligases HECT domain- and RCC1-like domain–containing proteins (HERCs; HERC5 in humans and HERC6 in mice)." (PMID 37651190, 2023). "Up-regulated differentially expressed genes (DEGs) indicated a clear relationship with the innate immune response against viral infection, including genes coding PRRs (LPG2 or DHX58) and IFN-stimulated genes (ISG15, Mx, STAT1, HERC5, IFI44, IFIT-1, NUP133, TRIM21)." (PMID 35215144, 2022). "The ESCRT, complex, ALIX-CHMP4A, is recruited to NS3 through their interactions with the putative L domain motif of NS3, while CHMP4A is recruited to E. In addition, we demonstrate the antiviral mechanism of ISG15 and HERC5, which degrades ALIX and CHIMP4A, indirectly targets virus infection." (PMID 34851141, 2022). "Regarding upregulated DEGs, a clear relationship with the innate immune response against viral infection was observed, being unigenes detected those coding pattern recognition receptors (PRRs) (DHX58), and IFN-stimulated genes (ISG15, Mx, STAT1, HERC5, IFI44, IFIT-1, NUP133, and TRIM21)." (PMID 30065724, 2018).
breast carcinoma (7 papers, 2022 to 2025). "In breast cancer, a group of bioinformatics studying breast cancer patients found that HERC5 was associated with lymph node metastasis and tumor grade and significantly affected patients’ prognoses." (PMID 36771004, 2023). "Weighted gene correlation network analysis identified HERC5 as prognostic candidate for breast cancer." (PMID 36807122, 2023). "HERC5 is identified to be a potential prognostic biomarker for breast cancer via bioinformatics analysis." (PMID 35064108, 2022). "For example, HERC1, HERC4, and HERC5 have been found to be overexpressed in human breast cancer and to promote cancer progression." (PMID 35889210, 2022). "HERC5 is revealed to be a prognostic biomarker for breast cancer through bioinformatic analysis." (PMID 35064108, 2022). "HERC5 was reported to be a latent prognostic index in breast cancer." (PMID 35637966, 2022). "Bioinformatic analysis indicated that HERC5 could serve as a prognostic biomarker in breast cancer." (PMID 35637966, 2022). "In breast cancer, RSAD2, along with HERC5 and CCL8, was identified as a crucial gene impacting prognosis through gene co-expression network analysis." (PMID 40510586, 2025).
hepatocellular carcinoma (5 papers, 2015 to 2023). A malignant tumor that arises from hepatocytes. "Thirdly, in hepatocellular carcinoma tissues, enzymes involved in the ISGylation process (including EFP, HERC5, UBA1 and USP18) are elevated compared with adjacent non‐tumour tissues." (PMID 36071546, 2022).
ovarian carcinoma (5 papers, 2017 to 2024). A malignant neoplasm originating from the surface ovarian epithelium. "Four of these factors (FGF18, HERC5, RPS27A, and hsa-miR-202) were found to be associated with ovarian cancer in previous literatures." (PMID 38182734, 2024). "HERC5 was found to have increased expression levels in topotecan-resistant ovarian cancer cell lines by34." (PMID 38182734, 2024). "Four of these factors (FGF18, HERC5, hsa-miR-202, and RPS27A) were found to be associated with ovarian cancer in previous literatures." (PMID 37609286, 2023). "Consistent with previous findings in topotecan-treated and -resistant ovarian cancer cells, we found that HERC5 was upregulated in LM after LDM topotecan treatment and in HT29-topotecan resistant cell lines." (PMID 33375322, 2020). "In addition, KLF4 was identified as a putative upstream regulator of drug resistance in ovarian cancer and together with ST3GAL5, SYNE1, CXCL8, HERC5, FOSL1, ARRDC4 merits further studies." (PMID 28473707, 2017).
COVID-19 (4 papers, 2022 to 2023). A disease caused by infection with severe acute respiratory syndrome coronavirus 2. "HERC5, which has direct antiviral function by catalyzing ISGylation38, was significantly downregulated in B_naive and B_memory of severe compared to moderate COVID-19." (PMID 37095364, 2023). "IFI44, OAS1, IFI44L, ISG15, and HERC5 are the five hub genes shared by RA, COVID-19, and SAB." (PMID 36189314, 2022).
lupus (3 papers, 2021 to 2025). "For example, using HERC5 gene expression in lymphoblastoid cell lines as a readout of the missense variant effect on USP18 protein function allowed us to establish a potentially causal link between reduced USP18 function and increased lupus risk." (PMID 41004399, 2025).
melanoma (3 papers, 2017 to 2024). A malignant, usually aggressive tumor composed of atypical, neoplastic melanocytes. "Further analysis of the TCGA melanoma cohort showed that HERC5 and FBXO32 expression covaried with MITF; however, they were not correlated significantly with survival of patients with metastatic cutaneous melanoma." (PMID 33462405, 2021).
colorectal cancer (2 papers, 2021 to 2023). A primary or metastatic malignant neoplasm that affects the colon or rectum. "ISGylated HERC5 material was also detected in the colorectal cancer cell line." (PMID 33214684, 2021).
glioma (2 papers, 2016 to 2017). A benign or malignant brain and spinal cord tumor that arises from glial cells (astrocytes, oligodendrocytes, ependymal cells). "We have also identified a four RBP (NOL3, SUCLG1, HERC5 and AFF3) signature, having a unique expression pattern in glioma stem-like cells (GSCs), to be an independent poor prognostic indicator in GBM." (PMID 28035070, 2017). "MMP7 codes for a metastatic promoting protein, HERC5 is an ubiquitin ligase that may be involved in malignancy, SLC7A11 is a part of the anionic amino acid transport system and was highly expressed in early stages of glioma, and LPHN2 has a role in cell adhesion." (PMID 26515461, 2016).
HIV-1 infection (2 papers, 2011 to 2012). The type species of lentivirus and the etiologic agent of acquired immunodeficiency syndrome (AIDS). "Interestingly, the interferon-induced cellular protein HERC5, which acts as a host restriction factor of HIV-1 infection, has been found to block both HIV-1 and MLV Gag particle assembly with a similar efficiency." (PMID 22348230, 2012). "Transcriptional profiling data revealed that HERC5 and ISG15 RNA expression are significantly increased in lymphatic tissue during acute HIV-1 infection in patients with asymptomatic and acute stages of AIDS and patients with AIDS." (PMID 22093708, 2011). "Given our data presented here that HERC5 inhibits HIV-1 particle production, one standing question is why HERC5 is not sufficient to suppress HIV-1 infection in patients who succumb to AIDS?" (PMID 22093708, 2011). "Furthermore, HERC5 and ISG15 were identified as correlates of protection from HIV-1 infection in controllers compared to non-controllers." (PMID 22093708, 2011).
acute myeloid leukemia (1 paper, 2024). Acute myeloid leukemia (AML) is a group of neoplasms arising from precursor cells committed to the myeloid cell-line differentiation. "Within the canine lymphoma group, HERC5 showed consistent upregulation, a gene similarly implicated in human acute myeloid leukemia but previously no reports exist." (PMID 39911484, 2024). "A recent study has indicated a downregulation of HERC5 expression in human acute myeloid leukemia; however, there are no related reports within the field of veterinary medicine." (PMID 39911484, 2024).
AIDS (1 paper, 2011). A syndrome resulting from the acquired deficiency of cellular immunity caused by the human immunodeficiency virus (HIV). "Our analysis of transcriptional profiling data of patient samples from various stages of infection and disease progression revealed that HERC5 expression is significantly increased in viremic patients (eg. acute, chronic, and AIDS)." (PMID 22093708, 2011). "With no apparent HIV-1 protein that directly counteracts it, HERC5 may represent a new candidate for HIV/AIDS therapy." (PMID 22093708, 2011).
Atrophy (1 paper, 2024). Any weakening or degeneration, especially through lack of use. "Genetic variants associated with decreased levels of pathogenic proteins ITGB6 (rs8099840), TLR5 (rs1403631, rs75118229), F7 (rs6046), HERC5 (rs406936) and MGA (rs704) were associated with preserved brain volumes over time, including in regions susceptible to infection-specific atrophy." (PMID 39143319, 2024).
dementia (1 paper, 2024). Loss of intellectual abilities interfering with an individual's social and occupational functions. "Further, RNA-seq data suggests low abundance of HERC5 and TRIM25 in brain samples analysed from individuals with aging, dementia or with traumatic brain injury, when compared with healthy subjects." (PMID 38431611, 2024).
dengue (1 paper, 2024). "This work provides insights into the NDI and vaccine-induced overlapping immune response and suggests molecular markers (e.g., IFIT5, ISG15, and HERC5) for anti-dengue-specific therapies and effective vaccination development." (PMID 38444851, 2024). "Among the ten strongest predictors of dengue severity, IFIT5, ISG15, and HERC5 were the three most important variables." (PMID 38444851, 2024).
germinoma (1 paper, 2010). A malignant germ cell tumor arising in the central nervous system. "Six genes (BANK1, CXCL9, CXCL11, DDIT4L, ELOVL6 and HERC5) within 4q13.3-4q28.3 were more abundant in germinomas." (PMID 20178649, 2010).
HCMV infection (1 paper, 2016). "qRT-PCR assays confirmed the efficient reduction of Herc5 transcript levels in cells expressing Herc5-specific shRNAs (shHerc5-1 and shHerc5-2) compared to in cells expressing control shRNA (shC) after UV-HCMV infection." (PMID 27564865, 2016). "Collectively, our results with UBP43, Herc5, UBE1L, and UbcH8 knockdown cells demonstrate an inverse relationship between ISGylation and HCMV growth, indicating a general inhibitory role of ISGylation in HCMV infection." (PMID 27564865, 2016).
inflammatory bowel disease (1 paper, 2025). A spectrum of small and large bowel inflammatory diseases of unknown etiology. "Inflammatory bowel disease was inversely associated with GATE scores for 5 interferon-stimulated genes—IFIT1, IFI44, HERC5, MX1, IFI44L—regulated by the same trans-expression quantitative trait locus, and with the GATE score for IFNL1." (PMID 40996888, 2025).
lipid metabolism disorders (1 paper, 2022). "Reduced β-catenin protein expression, increased lipid metabolism disorders, and cell apoptosis were detected in cells induced with HERC5 overexpression, which was reversible with the reactive oxygen species (ROS) inhibitor." (PMID 36259544, 2022). "In this study, HERC5 silencing upregulated β-catenin protein expression and inhibited lipid metabolism disorders and cell apoptosis." (PMID 36259544, 2022).
Listeria infection (1 paper, 2015). "We found that UBE1L (E1), UBE2L6 (E2), HERC5 and TRIM25 (E3s) mRNA are all significantly upregulated following Listeria infection, as is the deconjugating enzyme USP18." (PMID 26259872, 2015).
liver cancer (1 paper, 2020). An epithelial or non-epithelial malignant neoplasm that arises from the liver. "In conclusion, our study shows that expression of EFP, HERC5, UBA1 and USP18 genes, upregulated in tumour tissues of HCC patients, is correlated with liver function parameters and, thus, may be associated with the pathogenesis of liver cancer." (PMID 32132870, 2020).
lung carcinoma (1 paper, 2017). "It has been reported that the level of HERC5 is a prognostic marker in lung cancer; however, its role in drug resistance is unknown." (PMID 28611294, 2017).
lymphoma (1 paper, 2024). A malignant (clonal) proliferation of B- lymphocytes or T- lymphocytes which involves the lymph nodes, bone marrow and/or extranodal sites. "In the comparison between lymphoma dogs and controls, we found that the upregulation of HERC5 may be associated with the pathogenic mechanisms underlying canine lymphoma." (PMID 39911484, 2024).
oropharyngeal cancers (1 paper, 2019). Carcinoma, predominantly squamous cell, arising from the epithelial cells of the oropharynx. "A distinct set of prognosticators were identified for HPV+ and HPV- oropharyngeal cancers; ECHDC2, GGT6, HERC5 were showed to be associated with HPV+; HERC5 has a known anti-viral activity and its possible role in HNSCC HPV associated cancer is yet to be studied." (PMID 31310629, 2019).
ZIKV infection (1 paper, 2017). "ZIKV induction of the ISG15 family further suggests the potential for USP18-directed downregulation of IFN-α/β translation and for HERC5 to enhance IRF stability that may drive ISG induction during ZIKV infection." (PMID 28698279, 2017). "This study noted the induction of ATF3, EGR1, JUNB, IRF7, ISG15, HERC5/6, additional ISGs, chemokines CCL5 and CXCL10, prosurvival responses, and decreased proapoptotic genes, similar to gene induction levels we found to be induced by ZIKV infection of hBMECs (GEO GSE98889)." (PMID 28698279, 2017).